ABHD14B (abhydrolase domain containing 14B)
Description:
Acts as an atypical protein-lysine deacetylase in vitro. Catalyzes the deacetylation of lysine residues using CoA as substrate, generating acetyl-CoA and the free amine of protein-lysine residues. Additional experiments are however required to confirm the protein-lysine deacetylase activity in vivo (Probable). Has hydrolase activity towards various surrogate p-nitrophenyl (pNp) substrates, such as pNp-butyrate, pNp-acetate and pNp-octanoate in vitro, with a strong preference for pNp-acetate. May activate transcription.
Synonyms: CIB; MGC15429; HEL-S-299
Tractability: PROTAC: ubiquitination databases record sites on it; its protein half-life has been measured.
Target class: Enzyme; Transferase
Gene: Protein-coding gene on chromosome 3 (51,968,510 to 51,983,409, reverse strand). Ensembl gene ENSG00000114779.
Subcellular location: Cytoplasm; Nucleus
Subcellular location (Human Protein Atlas): Nucleoli; Nucleoplasm; Cytosol
Pathways (Reactome):
Metabolism: Cytosolic sulfonation of small molecules
Gene Ontology:
Molecular function: hydrolase activity; protein binding; protein-lysine-acetyltransferase activity
Biological process: positive regulation of transcription by RNA polymerase II; 3'-phosphoadenosine 5'-phosphosulfate metabolic process
Cellular component: cytoplasm; cytosol; extracellular exosome; nucleolus; nucleoplasm; nucleus
Genetic constraint (gnomAD): Loss-of-function variants: 20 observed, 15.75 expected, observed/expected ratio (o/e) 1.27, 90% interval 0.89 to 1.79. The synonymous counts are far from expectation, so gnomAD's model fits this gene poorly and the ratio says little. Missense variants: 243 observed, 275.79 expected, observed/expected ratio (o/e) 0.88, 90% interval 0.79 to 0.98. Synonymous variants: 92 observed, 121.87 expected, observed/expected ratio (o/e) 0.75, 90% interval 0.64 to 0.9.
Homologues: Orthologues: chimpanzee ABHD14B (99% identical), macaque ABHD14B (96% identical), guinea pig ABHD14B (87% identical), mouse Abhd14b (87% identical), pig ABHD14B (87% identical), rat Abhd14b (86% identical), dog ABHD14B (65% identical), zebrafish abhd14b (62% identical), rabbit ABHD14B (61% identical), tropical clawed frog abhd14b (61% identical), Drosophila melanogaster CG5704 (16% identical), Drosophila melanogaster CG15879 (14% identical), and 11 more. Paralogues in human: ABHD14A (42% identical), BPHL (26% identical), EPHX2 (23% identical), ABHD5 (20% identical), EPHX4 (20% identical), ABHD11 (18% identical), ABHD4 (18% identical), ABHD6 (18% identical), ABHD8 (18% identical), EPHX3 (18% identical), MEST (18% identical), SERHL2 (15% identical).
Diseases named in the same sentence as ABHD14B in open-access papers:
ABHD14B is named in the same sentence as 5 diseases in open-access papers, as found by Europe PMC text mining. Sharing a sentence is not in itself a finding about the gene and the disease. The quoted sentences say what the papers report.
lung carcinoma (2 papers, 2017 to 2023). "In addition, the specific roles of novel NRF2-targeted genes such as ABHD14B, LRP8, and SLC27A5 in lung cancer need to be investigated." (PMID 29050246, 2017).
tumor (1 paper, 2021). "While the expression levels of SEPT3, RAD51AP1, and EXO1 are higher in tumor-bearing patients, while ABHD14B is lower." (PMID 34646403, 2021).
ABHD14B also shares sentences with these, for which no sentence is quoted: cancer (1 paper); colorectal cancer (1); ovarian carcinoma (1).